SACK1C (scaffolding CK1 anchoring protein C)
Description:
May play a role in MAPK signaling.
Synonyms: FAM83C; C20orf128; dJ614O4.7
Tractability: No criterion of Open Targets' tractability assessment is met for any kind of drug.
Gene: Protein-coding gene on chromosome 20 (35,285,731 to 35,292,425, reverse strand). Ensembl gene ENSG00000125998.
Subcellular location: Cytoplasm
Gene Ontology:
Molecular function: protein binding; protein kinase binding
Biological process: signal transduction
Cellular component: cytoplasm
Genetic constraint (gnomAD): Loss-of-function variants: 27 observed, 28.18 expected, observed/expected ratio (o/e) 0.96, 90% interval 0.7 to 1.32. The upper end of that interval is the gene's LOEUF score, 1.32, which puts it in group 5 of 6, group 1 being the genes least tolerant of losing a copy. Missense variants: 984 observed, 1,012.1 expected, observed/expected ratio (o/e) 0.97, 90% interval 0.92 to 1.02. Synonymous variants: 426 observed, 425.19 expected, observed/expected ratio (o/e) 1, 90% interval 0.93 to 1.09.
Homologues: Orthologues: chimpanzee FAM83C (99% identical), macaque FAM83C (94% identical), pig FAM83C (82% identical), dog FAM83C (81% identical), rabbit FAM83C (81% identical), mouse Fam83c (78% identical), rat Fam83c (78% identical), guinea pig FAM83C (78% identical), zebrafish fam83c (31% identical), tropical clawed frog fam83c (28% identical). Paralogues in human: SACK1H (22% identical), SACK1G (20% identical), SACK1B (19% identical), SACK1A (19% identical), SACK1D (18% identical), SACK1E (17% identical), SACK1F (16% identical).
Diseases named in the same sentence as SACK1C in open-access papers:
SACK1C is named in the same sentence as 9 diseases in open-access papers, as found by Europe PMC text mining. Sharing a sentence is not in itself a finding about the gene and the disease.
SACK1C shares sentences with these, for which no sentence is quoted: cancer (4 papers); ovarian carcinoma (3); lung carcinoma (2); bladder cancer (1); breast carcinoma (1); cervical adenocarcinoma (1); cervical cancer (1); cervical squamous cell carcinoma (1); squamous cell carcinoma (1).